ASB17 (ankyrin repeat and SOCS box containing 17)
Description:
May be a substrate-recognition component of a SCF-like ECS (Elongin-Cullin-SOCS-box protein) E3 ubiquitin-protein ligase complex which mediates the ubiquitination and subsequent proteasomal degradation of target proteins.
Synonyms: ASB-17
Tractability: No criterion of Open Targets' tractability assessment is met for any kind of drug.
Gene: Protein-coding gene on chromosome 1 (75,918,873 to 75,932,404, reverse strand). Ensembl gene ENSG00000154007.
Pathways (Reactome):
Immune System: Antigen processing: Ubiquitination & Proteasome degradation
Metabolism of proteins: Neddylation
Gene Ontology:
Biological process: intracellular signal transduction; protein ubiquitination
Cellular component: cytosol; apical ectoplasmic specialization
Genetic constraint (gnomAD): Loss-of-function variants: 26 observed, 26.47 expected, observed/expected ratio (o/e) 0.98, 90% interval 0.72 to 1.36. The upper end of that interval is the gene's LOEUF score, 1.36, which puts it in group 5 of 6, group 1 being the genes least tolerant of losing a copy. Missense variants: 326 observed, 355.73 expected, observed/expected ratio (o/e) 0.92, 90% interval 0.84 to 1. Synonymous variants: 128 observed, 127.04 expected, observed/expected ratio (o/e) 1.01, 90% interval 0.87 to 1.17.
Homologues: Orthologues: chimpanzee ASB17 (99% identical), macaque ASB17 (99% identical), pig ASB17 (92% identical), rabbit ASB17 (90% identical), dog ASB17 (89% identical), mouse Asb17 (88% identical), rat Asb17 (87% identical), guinea pig ASB17 (78% identical), Drosophila melanogaster stops (21% identical).
Diseases named in the same sentence as ASB17 in open-access papers:
ASB17 is named in the same sentence as 1 disease in open-access papers, as found by Europe PMC text mining. Sharing a sentence is not in itself a finding about the gene and the disease.
ASB17 shares sentences with these, for which no sentence is quoted: inflammation (1 paper).